AKT1 (AKT serine/threonine kinase 1)
Diseases named in the same sentence as AKT1 in open-access papers (continued):
Sharing a sentence is not in itself a finding about the gene and the disease.
prostate carcinoma (continued). "AKT1, AKT2, and AKT3 activating mutations are rare in prostate cancer (≤0.9%, predominantly in AKT1 at E17K), whereas AKT1, AKT2, and AKT3 high-level gene amplification that can increase AKT activity is more common, particularly in advanced disease (up to 4.5%, 2%, and 4.7% incidence respectively)." (PMID 32630372, 2020). "Besides, because anticarcinogenic properties of naringenin have been reported in diverse malignant tumors prostate cancer pathway consisting of eight proteins was found: AKT1, MAPK1, IGF1R, AR, CCND1, INS, PIK3CA, IGF1." (PMID 30918758, 2019). "A high level of phosphorylated AKT1 is a strong predictor for prostate cancer recurrence." (PMID 31766290, 2019). "One reason may be that genetic alterations in the PIK3CA/Akt1/PTEN pathway are less frequent among Asian men with prostate cancer than among Caucasian men." (PMID 31227862, 2019). "In their first study, they investigated whether prostate cancer subtypes driven by distinct oncogenes, namely AKT1 or MYC, exhibit distinct metabolic profiles." (PMID 30791464, 2019). "Thus, Priolo and coworkers have shown that prostate cancer associated with predominant MYC overexpression display dysregulated lipid metabolism, while tumors with predominant AKT1 activation were associated with accumulation of aerobic glycolysis metabolites." (PMID 31366128, 2019). "Akt1 expression is frequently elevated in breast and prostate cancers." (PMID 30872976, 2019). "When analyzing pathways associated with colorectal and prostate cancers, we observed that miRNAs targeting both NMT1/2 and MetAP2 genes also regulate the expression of key genes involved in these pathways, including AKT1, GSK3B, BRAF, MAPK and many others." (PMID 29579063, 2018). "In order to study the effects of endothelial Akt1 suppression on prostate cancer cell metastasis in vivo, we utilised a tamoxifen-inducible, endothelial-specific Akt1-deficient mouse model and murine RM1 metastatic prostate cancer cell line of C57/BL6 origin." (PMID 29755115, 2018). "Moreover, they also observed that knockdown of Akt1 results in a reduction in β-catenin total protein expression in prostate cancer." (PMID 30445978, 2018). "However, in clinical prostate cancer samples, Akt1 and -2 were reportedly localized both in cytoplasm and nucleus, whereas Akt3 was observed in cytoplasm." (PMID 28483982, 2017). "To study the impact of activation-associated Akt1 mutants on cell behaviour, we used retroviral gene transfer to generate murine Tramp-C1 prostate cancer cells (TrC1) and Akt1 knock-out (Akt1−/−) mouse embryonic fibroblasts (MEF) stably expressing specific Akt1-eGFP fusion proteins." (PMID 28209968, 2017). "SDF-1α/CXCR4 signaling activates Akt1 in the lipid rafts of prostate cancer cells." (PMID 28072855, 2017). "The androgen-independent prostate cancer cell line PC-3 expresses only Akt1 and Akt2." (PMID 28903409, 2017). "However, this pathway is frequently activated in human prostate cancer as a result of genetic alterations that include the biallelic loss of PTEN and activating mutations in AKT1 and PIK3CA/B." (PMID 26910118, 2016). "Interestingly, we have also demonstrated that Akt1 pathway can negatively regulate tumor angiogenesis and vascular permeability and that Akt-independent mechanism also does exist in prostate cancer cells leading to cell survival." (PMID 25714023, 2015). "Expression level changes of AKT1 have been previously revealed in prostate cancer cell lines." (PMID 25371717, 2014). "Given the frequency of PTEN gene alterations in advanced human prostate tumors and expression of CXCR4 in these patients, Akt1 signaling may be a therapeutic target for advanced prostate cancer patients." (PMID 23902739, 2013). "We show that, in prostate cancer, AKT1(E17K) had a prevalence of 1.4%." (PMID 20407443, 2010). "Low frequency or lack of AKT1 (E17K) mutation was reported in prostate cancer (PC) patients." (PMID 39329938, 2024).
prostate carcinoma (continued). "Moreover, in another study, AKT1 and other kinases were detected in blood EVs from patients with various epithelial tumor types, which has implications for metastatic prostate cancer due to genomic abnormalities in the PI3K pathway, though the distinction between large and small EVs was not made." (PMID 38719996, 2024). "Moreover, GNE-493 was still cytotoxic in Akt1/2-silenced primary prostate cancer cells." (PMID 35296639, 2022). "We have identified targets such as AKT1, TNF, IL6, STAT3, and CTNNB1 in Osthole’s inhibition of prostate cancer, along with pathways including the TNF signaling pathway, the Interleukin-6-17 (IL-6-17) signaling pathway, and the prolactin signaling pathway." (PMID 40978029, 2025). "By activating the downregulation of Akt1 through the mediation of miR-520a-3p, the chemical EGCG was able to trigger programmed cell death in prostate cancer cells, as well as in tissue samples from patients." (PMID 40143065, 2025). "Analysis indicated that the 9 hub genes (AKT1, HSP90AA1, SRC, GSK3β, VEGFR2, RHOA, ENO1, PKM, and IL-2) play roles in MF treatment by participating in signaling pathways related to prostate cancer, lipid and atherosclerosis, and insulin resistance." (PMID 40051434, 2025). "Capivasertib is an oral selective pan-AKT inhibitor, which serves as a novel treatment option in advanced breast or prostate cancer in patients with PI3KCA, PTEN, or AKT1 alterations." (PMID 40122972, 2025). "AKT1, mTOR, CASP9, and BCL2 were identified as the top targets involved in the anti-prostate cancer resistance effect of the SR-CR drug pair." (PMID 38326539, 2024). "In colon cancer, GRPR enhances invasion through the RhoA/ROCK pathway, while in prostate cancer, GRPR overexpression promotes a malignant phenotype via activation of AKT1, PKCε, TYK2, and MST1 pathways." (PMID 39768218, 2024). "Own previous work revealed that cells with overexpression of the clinically relevant PH-domain mutant AKT1-E17K with aberrant activation of AKT accelerated DSB repair and improved the survival of TRAMPC1 prostate cancer cells (TrC1) upon IR." (PMID 35875130, 2022). "Combined inhibition of IGF-1R and the Src family non-receptor tyrosine kinases leads to an effective suppression of AKT1 and AKT2 activation and consequently to a decreased intratibial tumor growth of prostate cancer cells." (PMID 34064589, 2021). "In this study, we created prostate cancer CWR22rv1 cells with the double knockout of Akt1 and Akt2 genes through CRISPR/Cas9 method to investigate the effect of Akt in metastasis of prostate cancer." (PMID 33377281, 2021). "Univariate and multivariate regression analysis of genotypes and alleleof PTEN, AKT1, PI3K, AR, and AMACR genesin controls and patients with prostate cancer." (PMID 32484847, 2020). "Most of the genetic alterations in ESR1, PIK3CA, AKT1, and MAPK1 were amplifications, suggesting an excess expression in prostate cancer." (PMID 30918758, 2019). "In prostate cancer RAD001 was shown to induce cancer cell apoptosis and to completely reverse neoplasms in mice expressing human Akt1 in their prostates." (PMID 27821815, 2016). "The mRNA expression of AKT1, AKT2, and AKT3 are detected in both normal and prostate cancer tissues." (PMID 26318033, 2015). "Transient knockdown of AKT1, AKT2, or AKT3 using siRNA suppresses the proliferation of prostate cancer cells both in vitro and in vivo." (PMID 26318033, 2015). "The molecular mechanisms how AKT1 and AKT2 regulate proliferation and survival or prostate cancer cells has been extensively studied." (PMID 26318033, 2015).
prostate carcinoma (continued). "Western blotting experiments also showed that the protein levels of Akt1, phospho-Akt Ser473, phospho-Akt Thr308, PDK1, c-Myc, Skp2 in prostate cancer cells was decreased by triol treatment." (PMID 23785446, 2013). "We identified and validated four candidate genes (AKT1, PSMC1, STRADA, and TTK) that impaired growth when silenced in androgen receptor positive prostate cancer cells and enhanced the antiproliferative effects of antiandrogens." (PMID 22509301, 2012). "Additionally, KEGG pathway analysis revealed that AKT1, BCL2, CASP3, and TNF were significantly enriched genes involved in the function of several pathways, including pathways in cancer, Prostate cancer, Chemical carcinogenesis-receptor activation, and others." (PMID 41291087, 2025). "Subsequently, PPI network analysis was conducted on these targets using the STRING database, which suggested that genes such as AKT1, TNF, IL6, STAT3, and CTNNB1 might be key targets for Osthole in the treatment of prostate cancer." (PMID 40978029, 2025). "The down-regulation of AKT1 and mTOR expression and the up-regulation of CASP9 expression implied that the conduction of the Prostate cancer signaling pathway is blocked, then this pathway-mediated proliferation was stalled and apoptosis was significantly increased." (PMID 38326539, 2024). "AKT1, mTOR, and CASP9 were all located at the core of the Prostate cancer signaling pathway." (PMID 38326539, 2024). "The inhibitory effect of 7-O-galloyltricetiflavan (P15) on six bacterial species may be mediated through the lipid and atherosclerosis pathway, prostate cancer, adherens junctions, and targets such as SRC, MAPK1, and AKT1." (PMID 36770996, 2023). "For example, AKT2, but not AKT1, mediates survival and maintenance of PTEN-deficient prostate cancer." (PMID 35996134, 2022). "Yet to our knowledge, and following exploration of the TCGA PanCancer Atlas dataset available via cBioportal, an altered expression of AKT1, CAV1, THBS1, or TIMP2 has not been previously associated with progression to aggressive prostate cancer." (PMID 34596356, 2021). "Numerous protein kinases including AKT1, MAPK1/ERK, RPS6KA1/RSK1, cAMP-activated protein kinase (PKA), PAK1, PRKCI/nPKC-iota, PRKCE/nPKC-epsilon and PIM1 were reported to phosphorylate BAD in prostate cancer cells." (PMID 33668112, 2021). "In PTEN-deficient prostate cancer models, downregulation of AKT2, but not AKT1, promoted regression of prostate cancer xenografts through upregulation of p21 and the pro-apoptotic protein Bax, and downregulation of insulin-like growth factor receptor-1." (PMID 33276499, 2020). "In prostate cancer, PTK6 contributes to increased phosphorylation and activation of its substrates, such as AKT serine/threonine kinase 1 (AKT), CAS scaffolding protein family member 1 (p130CAS), and focal adhesion kinase (FAK), thereby promoting the tumor progression." (PMID 31447885, 2019). "In addition to PTEN alterations, alterations of other members of the PI3K signaling pathway are frequent in prostate cancer, involving alterations of PI3KCA (13%), PIK3R1 (6%), NF2 (3%), AKT1 (1.5%), and NF1 (1.5%)." (PMID 31366128, 2019). "In PTEN-deficient prostate cancer, AKT2, but not AKT1, mediates cellular survival and proliferation." (PMID 31470874, 2019). "In addition, PIK3CA, AKT1, and MAPK1 directly interacted with AR, which was a naringenin-mediated protein gene as well and participated in prostate cancer pathway." (PMID 30918758, 2019). "Our observation suggested that AKT3 can regulate the proliferation of prostate cancer cells independent of AKT1 or AKT2." (PMID 26318033, 2015). "To explore whether AKT1, STRADA, and TTK are altered in human prostate cancer, we assessed the copy number and expression status of these genes in a previously-reported human prostate cancer dataset." (PMID 22509301, 2012).
prostate carcinoma (continued). "Akt1 is a serine-threonine kinase that relays signals from phosphatidylinositol 3′ kinase (PI3K) by its phosphorylation of downstream targets and deregulation of this pathway is known to contribute to prostate cancer progression." (PMID 22509301, 2012). "For example, Akt-3 is not expressed in androgen receptor positive prostate cell lines and no constitutive activation of Akt-2 has been observed in prostate cancer cell lines while Akt-1 is constitutively activated in most prostate cancer cell lines." (PMID 16721361, 2006). "Therefore, a hypothesis is currently proposed that naringenin acts through a series of genes (ESR1, PIK3CA, AKT1, MAPK1, and AR) to control prostate cancer cell proliferation." (PMID 30918758, 2019). "A major finding from the current study is that the lack of Akt1 in HLECs promotes prostate cancer cell transendothelial migration in vitro and metastasis to the mouse lungs in vivo involving increased nuclear localisation of β-catenin and suppression of endothelial tight-junction proteins." (PMID 29755115, 2018). "LNCaP cell transfection studies with an Akt1 overexpression vector indicate that this effect may be mediated through the inhibition of the protein kinase B (Akt)/NF-kB/MMP-9 cascade pathway, which results in diminished invasiveness of the prostate cancer cells." (PMID 36826044, 2023). "For example, a recent study demonstrated that miR-149 could inhibit AR expression and reduce the activity of PI3K/Akt1 signaling in castrate-resistant cells and also regulate RGS17-mediated oncogenic effects revealing its tumor suppressor nature in prostate cancer." (PMID 36091792, 2022). "Thus, our data show that endothelial Akt1 knockdown, although does not modulate prostate tumour growth, it promotes prostate cancer metastasis to the lungs, and that nuclear β-catenin level in endothelial cells is an important determinant of prostate cancer lung colonisation in vivo." (PMID 29755115, 2018). "Thus activation of Akt signaling alone in the presence of PTEN is insufficient to induce prostate cancer although the deletion of Akt1 but not Akt2 (Akt1 is the predominant isoform found in mouse prostate) was sufficient to suppress the development of high-grade PIN lesions in PTEN+/- mice." (PMID 22454635, 2012). "Impact of liposomal loaded dexamethasone, Turmeric and doxorubicin and their non-liposomal analogue on GSK-3, p-AKT-1 and PIK-3 protein expression post 3- estradiol induced prostate cancer using ELISA technique." (PMID 38723038, 2024). "In addition, knockdown of AKT1 or AKT2, but not AKT3, facilitated cell migration via an increase in activity of integrin β1 in prostate cancer cells." (PMID 26741489, 2016).
melanoma (555 papers, 2003 to 2026). A malignant, usually aggressive tumor composed of atypical, neoplastic melanocytes. "The observed decrease in phosphorylation levels of BRAF, PI3K, AKT1, and mTOR is particularly relevant, as constitutive activation of these pathways has been strongly associated with melanoma growth and resistance to therapy." (PMID 40806647, 2025). "Spontaneous brain metastases are relatively rare in murine melanomas and have previously been linked to AKT1 activation." (PMID 37894325, 2023). "Previous studies suggested that AKT1 promoted the development of melanoma metastases, and its melanoma-derived mutation, AKT1E17K, activated focal adhesion kinase and promoted melanoma brain metastasis." (PMID 33897771, 2021). "and the activating E17K mutation in AKT1 was recently shown to promote brain metastasis formation and reduce survival in a melanoma mouse model study." (PMID 35008286, 2021). "We also found that high messenger RNA (mRNA) expression of AKT1 was associated with poor survival in melanoma patients in several studies." (PMID 30820351, 2019). "Mutation and increased phosphorylation of AKT1 were identified in different types of cancers, including melanoma, breast, esophageal, colorectal, endometrial, ovarian, and non-small cell lung cancers." (PMID 28301567, 2017). "A screen of 137 melanomas and 65 cell lines identified an activating mutation E17A in AKT1 (one patient) and AKT3 (one patient and two cell lines), all with concurrent BRAF mutations." (PMID 24743024, 2014). "In this study, we identified the same AKT1 E17K mutation reported previously in other cancers in the tumour from a melanoma patient." (PMID 18813315, 2008). "We analysed melanoma clinical specimens for the presence of mutations in AKT1, AKT2, and AKT3 that result in the E17K mutation identified previously in breast, ovarian, and colorectal cancers." (PMID 18813315, 2008). "Consequently, mutations in PTEN in melanoma reduce this inhibition and allow for high AKT1 levels, with AKT1 playing a major role in metabolic alterations, resistance to treatment, and melanoma invasiveness." (PMID 34831420, 2021). "The most prevalent mutation in Akt1, E17K, is located within the PH domain and is found in several solid tumors including breast (5.9%), colorectal (1.6%), lung (0.6%), and ovarian cancers (0.8%) as well as in melanoma (0.5%)." (PMID 33916378, 2021). "In 2008, Davies and his collaborators, analyzing a large panel of melanoma tissues and cells, have occasionally observed mutations of AKT1 and AKT3, but the contribution of these mutations in the melanocyte transformation process remains unclear." (PMID 33917181, 2021). "Moreover, MCM-2-index is correlated with lower survival rates and this protein in association with COX-2 and p-Akt1 contribute to cell-cycle dysregulation in melanoma." (PMID 34959411, 2021). "In addition, the p-Akt1-nuclear expression was associated with poorer cancer-specific survival in cutaneous (P < .0001), oral (P < .0001), and sinonasal (P = .001) melanomas." (PMID 30647870, 2018). "Rare activation mutations in the AKT1 or AKT3 isoforms have been found in sun-exposed melanoma subtypes, and AKT overexpression may be associated with melanoma growth in situ." (PMID 19949544, 2009). "We observed that BRAF-mutant melanoma cells expressing an active AKT1 mutant (E17K) displayed elevated levels of focal adhesion (FA) factors and phosphorylated focal adhesion kinase (P-FAK)." (PMID 39922199, 2025). "Phospho(Ser473)-AKT1 has been linked to nuclear translocation and activation of FOXO3 in melanocytes and melanoma." (PMID 40562100, 2025). "To determine where within melanosomes AKT1 is located, we trypsinized fibroblast- and melanoma cell-derived melanosomes to remove membrane proteins." (PMID 38719996, 2024).